FGF13 (fibroblast growth factor 13)
Diseases named in the same sentence as FGF13 in open-access papers (continued):
Sharing a sentence is not in itself a finding about the gene and the disease.
lung carcinoma (2 papers, 2017 to 2021). "FGF13/miR-504 is upregulated in a subset of lung cancer and is a facilitator of cancer progression." (PMID 34572448, 2021).
melanoma (2 papers, 2017). A malignant, usually aggressive tumor composed of atypical, neoplastic melanocytes. "Together, this might suggest a CD271/FGF13 axis as yet another regulatory mechanism of melanoma cell migration." (PMID 28852061, 2017). "Live cell-imaging based scratch-wound assays of melanoma cells with stable knock-down of CD271 revealed a significantly reduced cell migration (3.9fold, p = 1.2E-04) and a reduced expression of FGF13, CSPG4, HMGA2 and AKT3 major candidate regulatory genes of melanoma cell migration." (PMID 28852061, 2017). "Although FGF13 shows no statistical significant discrimination between melanoma primary tumors and metastases, we observed that subsets of melanoma metastases show high expression of either FGF13 or LYPD1." (PMID 28112719, 2017). "Since FGF13, CSPG4 and HMGA2 were not among the top up-regulated genes in the CD271high subset of brain metastases, these factors may not be involved in melanoma brain metastasis." (PMID 28852061, 2017).
polycystic ovary syndrome (2 papers, 2018 to 2023). A disorder that manifests as multiple cysts on the ovaries. "We sought to evaluate the associations between FGF13 in follicular fluid and oocyte developmental competence in patients with polycystic ovary syndrome (PCOS)." (PMID 30257687, 2018).
temporal lobe epilepsy (2 papers, 2024 to 2025). A localization-related (focal) form of epilepsy characterized by recurrent seizures that arise from foci within the temporal lobe, most commonly from its mesial aspect. "FGF13 has been shown to be upregulated in the hippocampus of a temporal lobe epilepsy mouse model, whereas knockdown of Fgf13 attenuated hyperexcitability in hippocampal cells." (PMID 39773461, 2025).
Type 2 diabetes (2 papers, 2023 to 2025). "Chronic inflammatory and neuropathic pain affects over 90% of patients with Type 2 diabetes, and links between FGF13 and diabetic neuropathy in mouse models and in humans have been reported." (PMID 40662354, 2025). "We further verified the changes in FGF13 in the islets of pre-diabetes and type 2 diabetes mouse models." (PMID 36675322, 2023).
type 2 diabetic nephropathy (2 papers, 2024 to 2025). "However, tissue-specific effects were observed, as FGF13 ablation in glomerular endothelial cells ameliorated type 2 diabetic nephropathy by inhibiting apoptosis." (PMID 40617800, 2025). "In glomerular endothelial cells of type 2 diabetic nephropathy (T2DN), FGF13 expression is upregulated." (PMID 40617800, 2025).
Alzheimer disease (1 paper, 2025). A progressive, neurodegenerative disease characterized by loss of function and death of nerve cells in several areas of the brain leading to loss of cognitive function such as memory and language. "Unfortunately, FGF13 was downregulated in the brain of both Alzheimer’s disease mouse model and patients, while overexpression of FGF13 could significantly improve neuronal damage in a rat model of Alzheimer’s disease." (PMID 40617800, 2025).
Arrhythmia (1 paper, 2020). Any cardiac rhythm other than the normal sinus rhythm. "Thus, mice may be more “protected” than humans to CaM depletion–induced NaV1.5-mediated arrhythmias because of expression of FGF13 rather than FGF12." (PMID 32870823, 2020).
bladder cancer (1 paper, 2019). "Of these, three hub genes involving angiotensin II receptor, type 2 (AGTR2), fibroblast growth factor 13 (FGF13), and lysophosphatidic acid (LPA) receptor 3 (LPAR3) (marked by red color) have been reported to participate in cell migration and angiogenesis in bladder cancer or lactotroph tumors." (PMID 31708963, 2019).
cutaneous melanoma (1 paper, 2025). A primary melanoma arising from atypical melanocytes in the skin. "Besides, in human cutaneous melanoma cells, upregulation of FGF13 leads to fewer cells arrest at the G0/G1 phase and more cells arrest at S phase, as well as a decline in the apoptosis of cells." (PMID 40617800, 2025).
diabetes (1 paper, 2023). "To confirm the dysregulation of FGF13 in diabetes, we examined FGF13 expression in the endocrine islets of IGT and diabetic mouse models." (PMID 36675322, 2023). "In addition, the molecular mechanisms underlying the downregulation of FGF13 expression in IGT and diabetes, as well as its role in various metabolic tissues, need to be further explored." (PMID 36675322, 2023). "In order to verify the potential of FGF13 in clinical applications, serum FGF13 protein levels in IGT and T2DM patients were detected by ELISA, and the involvement of FGF13 in the pathogenesis of diabetes was confirmed." (PMID 36675322, 2023). "Together, these results suggest that FGF13 can be treated as a novel biomarker of IGT, which may provide new targets for the diagnosis and treatment of pre-diabetes and T2DM." (PMID 36675322, 2023).
diabetic neuropathy (1 paper, 2025). A chronic, pathological complication associated with diabetes mellitus, where nerve damages are incurred due to diabetic microvascular injury involving small blood vessels that supply these nerves, resulting in peripheral and/or autonomic nerve dysfunction. "FGF13/Nav1.7 protein complex is a translationally relevant target associated with diabetic neuropathy." (PMID 40662354, 2025). "Given FGF13’s association with diabetic neuropathy in mouse models and that altered FGF13 expression has been observed in patients with T2DN, we evaluated in vivo efficacy of PW164 in the T2DN HFD model." (PMID 40662354, 2025). "Of seven rare variants in the SCN9A gene and one in the FGF13 meeting these criteria, the V1831F variant (NM_001365536.1 2:167055658_C/A c.5491G>T) in the SCN9A gene found in a painless diabetic neuropathy patient was particularly relevant." (PMID 40662354, 2025). "Thus, FGF13 is a rheostat of nociception and promising therapeutic target for diabetic neuropathy pain." (PMID 40662354, 2025). "Notably, the ratio of FGF13/Nav1.7 mean fluorescent intensity is upregulated in donor-derived DRG neurons from patients with T2DN, suggesting increased complex formation, and a rare genetic variant associated with painless diabetic neuropathy is a predicted hot spot at the FGF13/Nav1.7 complex." (PMID 40662354, 2025).
hearing loss (1 paper, 2025). "Collectively, these data suggested in an opposite direction that downregulation of FGF13 plays an important role in hearing loss in ARHL." (PMID 40617800, 2025). "Above all, the downregulation of FGF13 was statistically associated with hearing loss and the decrease in the number of SGNs, as well as the ribbon synapses." (PMID 40617800, 2025).
hypertrichosis (1 paper, 2016). Excessive hair growth anywhere on the body. "Hair growth was considered to be regulated by hairless gene, FOXI313, hypertrichosis gene, FGF13, Trps1, Sox914, 15, and hair overgrowth gene, ABCA516." (PMID 27796358, 2016).
left ventricular hypertrophy (1 paper, 2025). Enlargement of the LEFT VENTRICLE of the heart. "First, echocardiography results showed that upon treatment with D‐galactose, myocardial function exhibited abnormalities, characterized by left ventricular hypertrophy, and decreased ejection fraction and fractional shortening, while myocardial FGF13 deficiency mitigated these outcomes." (PMID 40184605, 2025).
lymph node metastasis (1 paper, 2021). "The transcription levels of CTGF, CYR61, FGF13, CHRDL1, and OGN were significantly higher in health controls than in THCA patients in the subgroup analyses involving disease stage, lymph node metastasis, gender, and age." (PMID 33816258, 2021).
metastatic melanoma (1 paper, 2017). A melanoma that has spread from its primary site to another anatomic site. "Further, we evaluated CSPG4 and FGF13 expression in MET and observed a non-significant or only partially significant difference in expression of CSPG4 or FGF13 among primary and metastatic melanoma, respectively." (PMID 28852061, 2017).
myeloid leukemia (1 paper, 2016). A clonal proliferation of myeloid cells and their precursors in the bone marrow, peripheral blood, and spleen. "The pathways and genes that significantly changed were classified as follows: cancer pathways (EPAS1, CCND1, FGF13), myeloid leukemia pathways (ZBTB16, KIT, IL13), hematopoietic cell lineage pathways (EPOR, GYPA, CD36) and so on." (PMID 27516205, 2016).
Myocardial fibrosis (1 paper, 2025). "Myocardial‐specific knockout and overexpression of FGF13 alleviated and exacerbated D‐galactose/Doxorubicin‐induced cardiac dysfunction, myocardial fibrosis, and aging characteristics in vivo, respectively." (PMID 40184605, 2025).
non-small cell lung carcinoma (1 paper, 2025). A group of at least three distinct histological types of lung cancer, including non-small cell squamous cell carcinoma, adenocarcinoma, and large cell carcinoma. "Align with our study, in non-small cell lung cancer, high levels of FGF13 inhibited the activity of P21 and P27, thus, enhancing the process of transition from G1 to S phase and promoting A549 cells proliferation." (PMID 40617800, 2025).
Parkinson disease (1 paper, 2025). A progressive degenerative disorder of the central nervous system characterized by loss of dopamine producing neurons in the substantia nigra and the presence of Lewy bodies in the substantia nigra and locus coeruleus. "Collectively, these findings indicate that FGF13 is decreased in the nigrostriatal tissues of both Parkinson's disease patients and parkinsonian mice." (PMID 40344619, 2025).
peripheral nerve injury (1 paper, 2023). Injury to a peripheral nerve. "In addition, FGF13-mediated microtubule stability is required to promote nerve repair after peripheral nerve injury, highlighting the potential therapeutic value of FGF13 in promoting the repair of injured nerves." (PMID 36675322, 2023).
pituitary adenomas (1 paper, 2023). "Studies performed on lactotroph pituitary adenomas highlighted aggressive behavior, especially in the male gender, when the expression of ERα was reduced, probably associated also with the expression of genes situated on chromosome X (CTAG2, FGF13, and VEGF) that influence the ER pathway." (PMID 37958702, 2023).
Sotos syndrome (1 paper, 2018). Sotos syndrome is a rare multisystemic genetic disorder characterized by a typical facial appearance, overgrowth of the body in early life with macrocephaly, and mild to severe intellectual disability. "FGF13 was associated with the differential expression of the MAPK pathway in Sotos syndrome." (PMID 30257687, 2018).
spinal cord injury (1 paper, 2023). Penetrating and non-penetrating injuries to the spinal cord resulting from traumatic external forces (e.g., WOUNDS, GUNSHOT; WHIPLASH INJURIES; etc.). "In a rat model of spinal cord injury (SCI), FGF13 was demonstrated to promote axon regeneration, by stabilizing microtubules and promoting mitochondria function." (PMID 36650549, 2023).
cancer (31 papers, 2007 to 2026). A tumor composed of atypical neoplastic, often pleomorphic cells that invade other tissues. "FGF13-mediated repression on ribosome biogenesis can reduce cell death caused by acute oncogene overexpression and promote cancer cell growth in vitro." (PMID 38791872, 2024). "Increased FGF13 expression has also been linked to cancer progression, and depletion of Fgf13 induces apoptosis in cancer cells." (PMID 34220452, 2021). "FGF13 has been found to promote cancer cell survival and growth by repressing ribosome biogenesis and restricting protein synthesis to reduce endoplasmic reticulum stress." (PMID 38791872, 2024). "OERCs were also evaluated for expression of FGF13, which has been related to cancer cell survival and tumor metastasis." (PMID 35205840, 2022). "Upregulated expression of FGF13 contributes to tumor growth, tumor invasion, and resistance to platinum drugs in some cancers." (PMID 35205840, 2022). "Itgb6 and Fgf13, which are involved in the pathogenesis of diseases such as cancer, exhibited higher expression levels in iF cells than in iTS-P cells." (PMID 33504014, 2021). "Since our initial publication of the findings summarized above, numerous studies have reported on FGF13′s actions to mitigate various cellular stresses in cancer cells." (PMID 33452347, 2021). "Despite the differences in cancer type and species between HeLa cisR and S180 cisR cells, expression of mouse FGF13 mRNA was strongly upregulated in S180 cisR cells, just as human FGF13 mRNA was upregulated in HeLa cisR cells." (PMID 24113164, 2013). "FGF13 has been found to play a role in cancer progression and treatment resistance." (PMID 39869563, 2025). "The possible involvement of Fgf13 in cancer has been reported." (PMID 33504014, 2021). "If high-level expression of FGF13 is detected in a cancer, then use of H1 receptor antagonists may be an effective approach to therapy." (PMID 33452347, 2021). "One of those reports proposed that FGF13 may serve as an enabler, allowing cancer cells to evade proteostatic stress triggered by oncogene activation." (PMID 33452347, 2021). "Fibroblast growth factor 13 (FGF13) is overexpressed in several types of cancer." (PMID 30867653, 2019). "As in lactotroph tumors in men, FGF13 is upregulated in cancer cells." (PMID 30555413, 2018). "MMP9, FN1, FGF13, and COL4A2 are significant genes in the pathways associated with cancer." (PMID 28191466, 2017). "Our results point to FGF13 as a novel target and useful prognostic guide for cancer therapy." (PMID 24113164, 2013). "Therefore, we can hypothesize a role for FGF13 in rewiring metabolism, specifically glucose metabolism, within cancer to promote progression." (PMID 41131959, 2026). "Both FGF13 and S100A1 have been suggested to promote cancer cell growth and survival by previous studies." (PMID 38791872, 2024). "Thus, the upregulation of fgf13 and the downregulation of ribosome biogenesis could occur temporally in response to endoplasmic reticulum stress during the formation of tumors to enhance the survivability of cancer cells." (PMID 38791872, 2024). "Therefore, targeting FGF13 should be examined carefully to determine whether the intentional or unintentional disruption of its intronic miR-504 may confound the effect in specific cancer types." (PMID 34572448, 2021).
cancer (continued). "In this report we show that FGF13/FHF2 plays a pivotal role in cellular platinum drug resistance and in reducing intracellular platinum concentrations in cancer cells." (PMID 24113164, 2013). "Although the augmented FGF13 expression in tumors is unlikely to be a cancer driver, it is not merely a passenger, because it allows the cancer cells to cope with undesirable side effects of oncogene activation." (PMID 30867653, 2019). "ROBO2 is also a candidate tumor suppressor gene; thus far, there is no clear evidence that FGF13, MAST4 and SPHKAP are associated with cancer development." (PMID 29117265, 2017). "LRP1B and ROBO2 are tumor suppressors, but FGF13, MAST4 and SPHKAP have not been associated with cancer development." (PMID 29117265, 2017). "This suggests FGF13 may provide a highly metastatic nature to these cancer cells that is not positively dependent on signaling by ERs." (PMID 33452347, 2021).
tumor (17 papers, 2013 to 2025). "Loss of Fgf13 dramatically limited the ability of the tumor cells to form colonies at the lung and re-expression of Fgf13 restored colonization ability." (PMID 31341204, 2019). "Treating tumor cells with Dkk-1 upregulated FGF-13, PLCB1, and MYC gene expression, which are key components in Ras, PI3K-MAPK, and Wnt signaling pathways." (PMID 36439519, 2022). "Neutralizing Dkk-1 and knocking down FGF-13 in tumor cells were able to reduce the extravasation rate." (PMID 36439519, 2022). "CDH3 was highly expressed in tumor samples, whereas high expression of CTGF, CYR61, OGN, FGF13, and CHRDL1 was associated with better prognosis and appeared to be a protective factor." (PMID 33816258, 2021). "CDH3 was found to be highly expressed, while CTGF, CYR61, CHRDL1, OGN and FGF13 had significantly lower expression in tumor tissues compared with peri-tumor tissues." (PMID 33816258, 2021). "In addition, FGF13 has extensive activities in promoting mitosis and cell survival, which participates in numerous biological processes, including embryonic development, cell growth, morphogenesis, tissue repair, tumor growth and invasion." (PMID 36213260, 2022). "In addition, loss of Fgf13 reduced in vitro cell migration, suggesting that Fgf13 may be critical for tumor cells to escape the primary tumor and to colonize the distal sites." (PMID 31341204, 2019). "Another tumor model BoC69 developed a remarkably high expression of FGF20 and FGF13 (59- and 18-fold, respectively)." (PMID 34271981, 2021). "Some, such as FGF13 and DDX3X, have earlier been shown to have a role in tumor behavior, though their dimorphic effects in males and females have not been identified." (PMID 34621669, 2021). "Comparing with peri-tumor controls, the expression of CTGF, CYR61, CHRDL1, OGN and FGF13 were significantly decreased, whereas CDH3 significantly increased in PTC tissues which were consistent with the bioinformatics results obtained by TCGA dataset." (PMID 33816258, 2021). "Moreover, FGF13, SEMA4D, PAPD6B and NRCAM were found to be commonly up-regulated in both cells and tumours." (PMID 30208958, 2018). "Fgf13 is a member of the FGF family, which possess broad mitogenic and cell survival activities and is involved in a variety of biological processes including embryonic development, cell growth, morphogenesis, tissue repair, tumor growth and invasion." (PMID 23554914, 2013). "Some show marked differential expression in a single non-SHH subgroup,such as NFIA (Group 3 tumours) and FGF13 (Group 4 tumours), orin more than one subgroup (e.g. TGIF2 and MYT1L), suggestingthat these genes may be relevant to MB in general." (PMID 24252690, 2013).
infection (2 papers, 2024 to 2025). The state of being infected such as from the introduction of a foreign agent such as serum, vaccine, antigenic substance or organism. "Indeed, infection with Fgf13-S but not Fgf13-VY increased K+ current density to WT levels." (PMID 38659789, 2024).
FGF13 also shares sentences with these, for which no sentence is quoted: pancreatic cancer (3 papers); developmental delay (2); Neurodevelopmental delay (2); ovarian carcinoma (2); triple-negative breast carcinoma (2); Wildervanck syndrome (2); acute myeloid leukemia (1); adenoma (1); adrenal cancer (1); Anxiety (1); depression (1); diabetic nephropathy (1); Failure to thrive (1); hepatocellular carcinoma (1); hereditary spastic paraplegia (1); hypertrophy (1); Impaired glucose tolerance (1); leukemia (1); liver cancer (1); metastatic cancers (1); mood disorder (1); neurodevelopmental disorder (1); neuronal migration disorders (1); paroxysmal dyskinesia (1); Prediabetes (1); rectal cancer (1); rectum tumors (1); schizophrenia (1); status epilepticus (1).